RGS9BP (regulator of G protein signaling 9 binding protein)
Description:
Regulator of G protein-coupled receptor (GPCR) signaling in phototransduction. Participates in the recovery phase of visual transduction via its interaction with RGS9-1 isoform. Acts as a membrane-anchor that mediates the targeting of RGS9-1 to the photoreceptor outer segment, where phototransduction takes place. Enhances the ability of RGS9-1 to stimulate G protein GTPase activity, allowing the visual signal to be terminated on the physiologically time scale. It also controls the proteolytic stability of RGS9-1, probably by protecting it from degradation (By similarity).
Synonyms: R9AP; FLJ45744; PERRS
Tractability: Antibody: UniProt predicts a signal peptide or a membrane-spanning region; the Human Protein Atlas places it where antibodies can reach.
Gene: Protein-coding gene on chromosome 19 (32,675,848 to 32,678,300, forward strand). Ensembl gene ENSG00000186326.
Subcellular location: Membrane
Subcellular location (Human Protein Atlas): Plasma membrane; End piece; Mid piece; Nucleoli; Principal piece
Pathways (Reactome):
Sensory Perception: Inactivation, recovery and regulation of the phototransduction cascade
Gene Ontology:
Biological process: detection of light stimulus involved in visual perception; G protein-coupled receptor signaling pathway
Cellular component: neuron projection; membrane; photoreceptor outer segment
Genetic constraint (gnomAD): Loss-of-function variants: 7 observed, 5.42 expected, observed/expected ratio (o/e) 1.29, 90% interval 0.71 to 1.9. That is too few expected variants to judge how well the gene tolerates losing a copy. Missense variants: 358 observed, 275.76 expected, observed/expected ratio (o/e) 1.3, 90% interval 1.19 to 1.42. Synonymous variants: 198 observed, 142.67 expected, observed/expected ratio (o/e) 1.39, 90% interval 1.24 to 1.56.
Homologues: Orthologues: chimpanzee RGS9BP (99% identical), macaque RGS9BP (99% identical), rabbit RGS9BP (85% identical), guinea pig RGS9BP (83% identical), mouse Rgs9bp (83% identical), rat Rgs9bp (83% identical), pig RGS9BP (81% identical), dog RGS9BP (73% identical), tropical clawed frog rgs9bp (59% identical), zebrafish RGS9BP (52% identical), Drosophila melanogaster CG14340 (17% identical), Drosophila melanogaster dcma (14% identical). Paralogues in human: RGS7BP (18% identical).
Diseases named in the same sentence as RGS9BP in open-access papers:
RGS9BP is named in the same sentence as 6 diseases in open-access papers, as found by Europe PMC text mining. Sharing a sentence is not in itself a finding about the gene and the disease.
RGS9BP shares sentences with these, for which no sentence is quoted: bradyopsia (2 papers); infection (1); myopia (1); oligocone trichromacy (1); retinal degeneration (1); retinopathy (1).